APOC1 (apolipoprotein C1)
Diseases named in the same sentence as APOC1 in open-access papers (continued):
Sharing a sentence is not in itself a finding about the gene and the disease.
cervical cancer (7 papers, 2021 to 2026). A primary or metastatic malignant neoplasm involving the cervix. "The genes SQLE, APOC1, H1.2, GCH1, and EEF1A1 were determined to be associated with cervical cancer." (PMID 41583517, 2026). "According to research, APOC1 functions as an oncogene in cervical cancer, and its knockdown both in vitro and in vivo reduces the proliferation of cervical cancer cells." (PMID 36908705, 2023). "The clinical outcome of cervical cancer patients is highly correlated with the relative expression of APOC1." (PMID 36908705, 2023). "Based on three genes of APOD, APOC1, and SQLE, the risk prediction model for the prognosis of patients with cervical cancer was established, tested and validated." (PMID 36536343, 2022). "In the study, APOD, APOC1 and SQLE were identified as prognostic genes, and a prognostic genes-based risk model was constructed and validated, which will provide a novel viewpoint and reference value for the treatment and prognosis of cervical cancer." (PMID 36536343, 2022). "In our enrichment analysis, lipid metabolism alteration mostly corresponds to the overexpression of the APOC1 gene in ASCC, which has been also found to be upregulated in HPV-positive cervical cancer." (PMID 40559621, 2025). "Simultaneously, the mRNA expression of APOD, APOC1, and SQLE was further assayed in cervical cancer tissues and normal tissues." (PMID 36536343, 2022). "Silencing of APOC1 restrained cell progression and EMT in cervical cancer cell lines, while APOC1 overexpression remarkably accelerated tumour progression and EMT (P < 0.05)." (PMID 34857818, 2021). "After one-way and multivariate analysis of variance, we finally obtained three prognostic genes of APOD, APOC1 and SQLE significantly related to survival, and the expression of which was assayed in 10 cervical cancer tissue samples and 10 normal samples by RT-qPCR." (PMID 36536343, 2022).
glomerulosclerosis (7 papers, 2022 to 2024). A hardening of the kidney glomerulus caused by scarring of the blood vessels. "Apoc1-Tg mice exhibited albuminuria, renal dysfunction, glomerulosclerosis, inflammatory cell infiltration, and increased inflammatory cytokine and fibrotic growth factor expression, suggesting that Apoc1 may play a role in DN pathogenesis." (PMID 38625739, 2024). "Recent studies have illuminated that APOC1 could be detected in the kidneys of diabetic patients, suggesting that APOC1 may be involved in glomerulosclerosis." (PMID 39511608, 2024). "Research revealed that APOC1 plays a role in the pathogenesis of glomerulosclerosis." (PMID 37305534, 2023).
Sepsis (7 papers, 2019 to 2025). Sepsis is defined as life-threatening organ dysfunction caused by a dysregulated host response to infection. "Sepsis often leads to reduced levels of HDL-C and its associated apolipoproteins, ApoA1, and apolipoprotein C1 (ApoC1)." (PMID 39057711, 2024). "Thus, the plasma levels of apoC1 were drastically reduced in patients with advanced sepsis, but were restored to normal levels in survivors, leading to the conclusion that apoC1 level is predictive for the evolution of a severe sepsis." (PMID 31779116, 2019).
Cognitive impairment (6 papers, 2018 to 2025). Abnormal cognition is characterized by deficits in thinking, reasoning, or remembering. "For example, it has been shown that genetic polymorphisms in APOE and APOC1 genes are associated with cognitive impairment progression in patients with late-onset AD." (PMID 35839250, 2022). "But the specific mechanisms by which APOC1 gene modulates the risk of cognitive impairment remain controversial, although some research has been done in this field." (PMID 31760383, 2019). "The APOC1 gene encodes apolipoprotein C1, a key regulator of the metabolism of high-density and very-low density lipoproteins, and may be associated with cognitive impairment in Chinese." (PMID 30443289, 2018). "Furthermore, APOC1 could increase the risk of cognitive impairment by modulating lipid metabolism." (PMID 31760383, 2019). "Mediation analysis was conducted to test whether adjusted APOC1 levels in peripheral blood measured at baseline influenced cognitive impairment through their effects on CTh." (PMID 40369256, 2025). "We detected recurring polymorphisms on chromosome 19 in the non-coding region upstream of the APOC1 gene (rs10414043) and in the APOE gene (rs429358 and rs769449) and identified a possible mechanism whereby these substitutions contribute to cognitive impairment." (PMID 37953886, 2023).
lymph node metastasis (6 papers, 2021 to 2024). "Logistic regression analysis identified that pathological stages T3/4, lymph node metastasis (PR/PD), residual tumours (R1/R2), and a Gleason score >7 as risk factors for high APOC1 expression in PCa." (PMID 39098992, 2024). "We also analyzed the diagnostic value of APOC1 mRNA expression in different stages, grading, lymph node metastasis, and distant metastasis." (PMID 36969562, 2023). "Univariate and multifactorial analyses showed that high expression of APOC1mRNA, lymph node metastasis, and sex were associated with OS of patients with ESCC, and APOC1 mRNA was likely an independent prognostic risk factor for OS in patients with ESCC." (PMID 36969562, 2023). "Subgroup analysis also revealed that the higher the cancer stage and lymph node metastasis, the higher the expression of APOC1." (PMID 36908705, 2023). "Based on subgroup analysis of CRC individual cancer stages and lymph node metastasis, it was discovered that APOC1 expression increased with increasing cancer stage and lymph node metastasis." (PMID 36908705, 2023).
type 1 diabetes (6 papers, 2011 to 2024). "A discrepancy was observed between the APOC1 LonGP results in the discovery and the validation dataset, by which the changes were associated with the type 1 diabetes diagnosis and seroconversion, respectively." (PMID 37743383, 2023). "The causal connection between low APOC1 levels and type 1 diabetes, and the mechanisms involved, remain to be explored." (PMID 37743383, 2023). "Nevertheless, we were able to verify that decreased serum levels of two peptides representing APOC1, were associated with rapid progression to type 1 diabetes." (PMID 37743383, 2023). "The measurements revealed how the levels of two peptides representing APOC1 decreased after seroconversion and remained lower in children who developed type 1 diabetes." (PMID 37743383, 2023). "To conclude, lower APOC1 levels are detected during the presymptomatic period of type 1 diabetes and in recently diagnosed patients whereas higher APOC1 levels are observed in adult patients." (PMID 37743383, 2023). "Targeted proteomics analysis of the selected candidates revealed that the levels of two peptides from APOC1 distinguished the children who progressed to type 1 diabetes from AAb− children." (PMID 37743383, 2023). "In addition, levels of ApoC1 are reduced at the onset of type 1 diabetes, and further studies are needed to explore the role of ApoC1 in the development of type 1 diabetes." (PMID 37537394, 2023). "The elevation of plasma TG levels in most diabetic patients might explain only in part this phenomenon since our study in type 1 diabetics showed significantly elevated apoC1 despite TG levels similar to that of control subjects." (PMID 36471375, 2022). "Accordingly, we could confirm in vivo that the electrostatic properties of apoC1 were modified in type 1 diabetic patients." (PMID 36471375, 2022).
carotid atherosclerosis (5 papers, 2011 to 2022). A thickening and loss of elasticity of the walls of carotid arteries that occur with formation of atherosclerotic plaques. "However, other studies evidenced a higher enrichment of apoC1 in VLDL in patients with carotid atherosclerosis compared to controls and a positive correlation between apoC1 enrichment of VLDL and carotid plaque area for VLDL analysed in the fasting state, but not in the postprandial phase." (PMID 36471375, 2022). "Oxidative ApoC1 and its oxidative-truncated form were specifically detected in HDL from patients with atherosclerotic vascular disease (ASVD), including CAD, carotid atherosclerosis, and ischemic stroke." (PMID 26090384, 2015). "Therefore, oxidation of ApoC1 may be a useful marker for predicting CAD, carotid atherosclerosis, or stroke." (PMID 26090384, 2015).
esophageal squamous cell carcinoma (5 papers, 2023 to 2025). Esophageal squamous cell carcinoma (ESCC) is a type of esophageal carcinoma (EC) that can affect any part of the esophagus, but is usually located in the upper or middle third. "Two key mRNAs related to esophageal squamous cell carcinoma, APOC1 and CEP55, and miRNAs closely associated with them, including hsa-miR-378a, hsa-miR-145, and hsa-miR-504, were identified using expression and survival analyses." (PMID 38172247, 2024). "By combining expression analysis, survival analysis, and wet and dry research validation, a key pathway (hsa-miR-378-5p-APOC1/CEP55) of esophageal squamous cell carcinoma progression after neoadjuvant immunotherapy was identified." (PMID 38172247, 2024). "In this study, we found that APOC1 was also highly expressed in cancer tissues after neoadjuvant immunotherapy for esophageal squamous cell carcinoma, which is consistent with other studies." (PMID 38172247, 2024). "After validation using survival analysis and dry-lab and wet-lab-based studies, we identified the I-miR-378-5p-APOC1/CEP55 as a critical pathway for esophageal squamous cell carcinoma progression after neoadjuvant immunotherapy." (PMID 38172247, 2024). "This pathway demonstrates that miR-378a-5p acts as an active tumor suppressor by targeting and regulating APOC1 and CEP55 during the onset and progression of esophageal squamous cell carcinoma." (PMID 38172247, 2024). "Immune infiltration analysis demonstrated that the expression of APOC1 and CEP55, the purity of esophageal squamous cell carcinoma cells, and numerous immune infiltration cells were closely related." (PMID 38172247, 2024). "The results demonstrated that the expression of APOC1 and CEP55 and the purity of esophageal squamous cell carcinoma cells were correlated (p < 0.05)." (PMID 38172247, 2024). "The analysis showed that APOC1 and CEP55 were significantly upregulated in esophageal squamous cell carcinoma tissues, which was consistent with our analysis results." (PMID 38172247, 2024). "Furthermore, we compared the highly expressed genes of APOC1+ APOE+ macrophages enriched in esophageal squamous cell carcinoma (ESCC) lymph nodes, which exhibit a similar tendency to lymph node metastasis as OSCC." (PMID 39236316, 2024). "Finally, high numbers of MΦ co-expressing APOC1 and APOE were found in metastatic lymph nodes of esophageal squamous cell carcinoma, a cancer with a metastatic pattern similar to OSCC." (PMID 40432828, 2025). "Subsequently, when we performed PCR validation on surgical specimens after neoadjuvant immunotherapy, we found that APOC1 and CEP55 were significantly upregulated and hsa-miR-378a-5p and hsa-miR-378a-3p were considerably downregulated in esophageal squamous cell carcinoma samples." (PMID 38172247, 2024). "Global single-cell transcriptome analysis using data from clinical trials demonstrated that TAMs highly expressed APOE, APOC1, and SPP1 genes in patients with esophageal squamous cell carcinoma (ESCC) post-neoadjuvant chemotherapy, and this leads to an increase in M2-like macrophages." (PMID 38787372, 2024).
glioma (5 papers, 2022 to 2025). A benign or malignant brain and spinal cord tumor that arises from glial cells (astrocytes, oligodendrocytes, ependymal cells). "Most recently, this has been underlined by the finding that ApoC1 can reduce the activity of ferroptosis pathways in glioma, thus propagating tumor growth." (PMID 36101402, 2022). "The immunomodulatory effect of ApoC1 on macrophages and microglia could help glioma cells to induce an immune escape-like metabolic state." (PMID 36101402, 2022). "Likewise, the expression of ApoC1 in central nervous system tumors has been demonstrated, but little information is available on its prognostic impact." (PMID 36101402, 2022). "Indeed, an increase in macrophages expressing high levels of Spp1, ApoE, Apoc1, Lgals3, and Gpnmb has been documented in glioma models, with high‐grade gliomas exhibiting a greater abundance of these macrophages compared to low‐grade gliomas." (PMID 40395129, 2025). "Of the genes identified by LASSO analysis, APOC1 and IFI30 expression levels in glioma were favorably correlated with the majority of immune cells, immunostimulators, immunoinhibitors, MHC molecules, chemokines, and chemokine receptors." (PMID 41438761, 2025). "Moreover, single‐cell RNA sequencing analyses of glioma samples have identified a TAM subset characterised by high SPP1 expression, alongside other gene markers such as FTL, LAPTM5, S100A11, APOC1, and APOC2." (PMID 40395129, 2025). "Our findings revealed a positive correlation between the expression levels of APOC1 and IFI30 in glioma and the majority of cytokines, while a negative correlation was observed between their methylation status and these cytokines." (PMID 41438761, 2025).
Hypertension (5 papers, 2011 to 2024). The presence of chronic increased pressure in the systemic arterial system. "For instance, decreased APOA4, APOC1, and APOC3 expression would result in reduced lipid removal from the vascular wall and inhibition of lipoprotein lipase activity, potentially promoting lipid accumulation, which might be associated with hypertension." (PMID 34929167, 2022).
triple-negative breast carcinoma (5 papers, 2022 to 2025). An invasive breast carcinoma which is negative for expression of estrogen receptor (ER), progesterone receptor (PR), and human epidermal growth factor receptor 2 (HER2). "APOC1 testing could also differentiate between triple-negative breast cancer patients and non-triple-negative breast cancer patients." (PMID 38067270, 2023). "This list was further filtered through a triple-negative breast cancer (TNBC) scRNA-Seq dataset by applying a stringent criteria selection (i.e., high expression restricted to the macrophage cluster), leading to 4 genes: SPP1, APOC1, FCER1G, and MMP9." (PMID 39808498, 2025).
atopic dermatitis (4 papers, 2017 to 2024). "From neurodegenerative diseases to atopic dermatitis, apoC1 remains a remarkable therapeutic target for future studies." (PMID 31779116, 2019).
ischemic stroke (4 papers, 2016 to 2022). A stroke disorder caused by obstruction of blood flow to the brain, due to thrombotic (local blood clot formation) or embolic (due to a blood clot or other material traveling from another site) event. "Furthermore, APOC1 is closely associated with vascular inflammation and retinitis pigmentosa, and reports have indicated that FGB is closely related to elevated plasma fibrinogen levels and ischemic stroke." (PMID 27416065, 2016). "Taken together, these findings suggest that APOC1 and APOC3 can be markers of hemorhagic stroke, but not of the ischemic stroke subtypes." (PMID 31242583, 2019).
liver cancer (4 papers, 2014 to 2025). An epithelial or non-epithelial malignant neoplasm that arises from the liver. "Another study has proved that inhibiting APOC1 facilitates the transition of M2 to M1 macrophages via the ferroptosis pathway, enhancing the efficacy of anti-PD1 immunotherapy in liver cancer." (PMID 40520002, 2025).
osteosarcoma (4 papers, 2020 to 2025). A usually aggressive malignant bone-forming mesenchymal neoplasm, predominantly affecting adolescents and young adults. "Recent studies have found that APOC1 promotes osteosarcoma progression through binding to MTCH2, and preoperative APOB/APOA1 has been identified as an independent prognostic factor for osteosarcoma in children and adolescents." (PMID 38212768, 2024). "Although seldom previous studies have revealed the expression and role of VAMP8, APOC1 and A2M in osteosarcoma, exploration in some other tumors has well proved that these genes are important tumor-related regulatory factors." (PMID 32665038, 2020). "The evidence indicated significant upregulation of APOC1 and MTCH2 expression in osteosarcoma SAOS-2 cells." (PMID 39511608, 2024). "In line with our findings, another report examined the interaction mechanism between APOC1 and mitochondrial carrier homolog 2 (MTCH2) in osteosarcoma." (PMID 39511608, 2024). "VAMP8, A2M, HLA-DRA, SPARCL1, HLA-DQA1, APOC1 and AQP1 were identified continuously upregulating during the oncogenesis and metastasis of osteosarcoma." (PMID 32665038, 2020).
ovarian carcinoma (4 papers, 2023 to 2025). A malignant neoplasm originating from the surface ovarian epithelium. "In our in vitro cellular assays, we discovered that APOC1 promotes the proliferation, migration, and invasive abilities of ovarian cancer cells." (PMID 38515073, 2024). "The Kaplan-Meier overall survival analysis revealed that ovarian cancer patients with high expression of APOC1 exhibited poorer overall survival compared to patients with low expression of APOC1." (PMID 38515073, 2024). "One study suggested that APOC1 could promote the estrogen receptor expression in the context of ovarian cancer." (PMID 40182431, 2025). "Among these, ovarian cancer ranked sixth in terms of APOC1 alterations." (PMID 38515073, 2024). "Furthermore, our study demonstrated that APOC1 exerted a crucial function in promoting the capacity of ovarian cancer cells to proliferate, migrate, and invade." (PMID 38515073, 2024). "Nevertheless, there is currently no report on the presence of APOC1 in ovarian cancer (OV)." (PMID 38515073, 2024).
renal carcinoma (4 papers, 2020 to 2024). A carcinoma arising from the epithelium of the renal parenchyma or the renal pelvis. "Subsequently, we investigated whether APOC1 was expressed in renal cancer cell lines (786-O, 769-P, CAKI-1, CAKI-2, and ACHN) and normal cell line HK-2." (PMID 32974161, 2020). "However, the role of APOC1 in renal cancer has not been elucidated." (PMID 32974161, 2020).
colon cancer (3 papers, 2014 to 2024). "Data from the Human Protein Atlas analysis showed that CRC patients, including those with rectum and colon cancer, had high or low expression of the APOC1 protein." (PMID 36908705, 2023).
Hypercholesterolemia (3 papers, 2019 to 2022). An increased concentration of cholesterol in the blood. "In addition, it is known that GALNT2, LPA, SCARB1, and APOC1 are genes responsible for a hereditary form of hypercholesterolemia." (PMID 35203469, 2022).
kidney cancer (3 papers, 2021 to 2022). Primary or metastatic malignant neoplasm involving the kidney. "According to the Oncomine database, we found that among all cancer types, the greatest upregulation of apolipoprotein C1 (ApoC1) was observed in kidney cancer samples." (PMID 36620603, 2022). "In particular, ELF5, SLC17A3, RALBP1, WNK1, APOC1, and CRYAB were experimentally verified to play an important role in the occurrence and development of kidney cancer." (PMID 34445498, 2021).
memory impairment (3 papers, 2018 to 2025). "In a study involving elderly individuals with memory impairment, those carrying the APOC1 risk genotype exhibited smaller HV compared to non-carriers, suggesting that APOC1 variants may contribute to AD-like neurodegeneration." (PMID 40369256, 2025).
primary progressive aphasia (3 papers, 2018 to 2022). Primary progressive aphasia (PPA) is a neurodegenerative disorder, characterized by a primary dissolution of language, with relative sparing of other mental faculties for at least the first 2 years of illness. "According to research, frontotemporal dementia and primary progressive aphasia are both caused by APOC1." (PMID 36699066, 2022). "LD (r2 = .35) between TOMM40 (rs2075650) and APOC1 (rs1064725) was observed in primary progressive aphasia (PPA), but not in controls and in behavioral variant fronto‐temporal dementia (bvFTD)." (PMID 32472747, 2020).